MIF (macrophage migration inhibitory factor)
Diseases named in the same sentence as MIF in open-access papers (continued):
Sharing a sentence is not in itself a finding about the gene and the disease.
heart diseases (5 papers, 2016 to 2025). "Evidence suggests that MIF has diverse functions in cardiac disease, largely depending on the underlying etiology." (PMID 40092999, 2025). "Macrophage migration inhibitory factor (MIF) is an important immune modulator that has been shown to be involved in the pathogenesis of different heart diseases, so understanding pathogenic variants of the MIF gene is important for risk stratification." (PMID 38476376, 2024). "The pleiotropic proinflammatory cytokine macrophage migration inhibitory factor (MIF) is involved in the pathogenesis of many human disease conditions, including heart diseases and inflammatory cardiomyopathies." (PMID 40092999, 2025). "Therefore, it is evident that MIF is a novel biomarker for heart disease and is worthy of further study in the future." (PMID 30983881, 2019). "Nevertheless, it has been shown that MIF plays an important role in heart disease." (PMID 27014277, 2016). "MIF and CXCL12 are considered as a potential biomarker for heart diseases in patients with T2DM." (PMID 35663309, 2022).
hematologic malignancies (5 papers, 2017 to 2024). "MIF is elevated in multiple hematologic malignancies, including lymphoma, Chronic Lymphocytic Leukemia (CLL), Acute Myelogenous Leukemia (AML), and ALL, where it is correlated with adverse outcomes." (PMID 38732068, 2024). "Though DDT’s role in hematologic malignancies is unexplored, studies are underway (NCT03918655) to evaluate the prognostic value of MIF during the treatment of FMS-like tyrosine kinase 3 mutated AML." (PMID 38732068, 2024).
psychiatric disorder (4 papers, 2017 to 2025). A disorder characterized by behavioral and/or psychological abnormalities, often accompanied by physical symptoms. "Considering our results and the findings of previous studies, further elucidation is required for not only the pathological but also neuroprotective role of MIF in neurological and psychiatric diseases via HIF pathway under hypoxic conditions." (PMID 35324982, 2022). "Interestingly, an imbalance in cytokines such as IL-6, TNF, IFN-γ, MIF, IL-17, TGF-β1, and IL-8 are correlated to psychiatric disorders." (PMID 40333139, 2025).
CNS tumor (3 papers, 2022 to 2024). "Macrophage migration inhibitory factor expression has been observed in several primary CNS tumor types." (PMID 39233830, 2024). "The second challenge for the use of MIF-targeting agents in primary CNS tumors is mitigating neurological off-target effects to reduce toxicity." (PMID 39233830, 2024). "There have been many MIF-targeting strategies developed that are at various stages in preclinical testing and clinical evaluation, some of which are in primary CNS tumors." (PMID 39233830, 2024). "Further research is needed to evaluate the potential role of genetic and epigenetic MIF regulation in primary CNS tumors." (PMID 39233830, 2024). "In this review, we summarize the latest functions of MIF in primary CNS tumor initiation and progression." (PMID 39233830, 2024). "Chimeric compounds may represent the next generation of MIF targeted therapies; however, these compounds remain to be studied in preclinical models of primary CNS tumors." (PMID 39233830, 2024). "Macrophage migration inhibitory factor (MIF) is a cytokine implicated in multiple tumorigenic processes such as cell proliferation, vascularization, and immune evasion and is therefore a promising therapeutic target in primary CNS tumors." (PMID 39233830, 2024). "More broadly, many orthosteric MIF inhibitors have not been tested in primary CNS tumor models." (PMID 39233830, 2024).
respiratory diseases (3 papers, 2022 to 2024). "Despite several studies in various respiratory diseases, including COPD and IPF or age related lung diseases, it is not clear if MIF is detrimental or protective." (PMID 36207373, 2022).
gastrointestinal disease (2 papers, 2013 to 2014). A disease that occurs in the gastrointestinal system, excluding the hepatobiliary system. "Since epithelial cells have previously been shown to be a source of MIF in gastrointestinal diseases, here we also examined cultured fibroblasts cells from human tissues for MIF expression." (PMID 24887129, 2014).
colonic polyp (1 paper, 2024). "In reverse MR analysis, it supports that colonic polyp led to a reduced expression of MIF and a rise in CTACK." (PMID 39439893, 2024).
genetic disease (1 paper, 2019). "This analysis may set the basis to encourage future clinical trials for anti-MIF drugs in disease like DMD, that despite being considered only a genetic disease, is characterized by in important involvement of inflammation." (PMID 31752120, 2019).
hematological cancers (1 paper, 2019). "The anti-CD74 mAb milantuzumab is currently being studied in phase I/II studies for hematological cancers and could represent a potential pharmacological candidate for MIF-DDT tailored interventions." (PMID 31752120, 2019).
MIF also shares sentences with these, for which no sentence is quoted: acute myocardial infarction (11 papers); bipolar disorder (5); experimental autoimmune encephalomyelitis (5); Guillain-Barre syndrome (5); idiopathic pulmonary fibrosis (5); chronic periodontitis (4); Dengue hemorrhagic fever (4); gastritis (4); renal failure (4); celiac disease (3); chronic myelogenous leukemia (3); leukocytosis (3); adenoid cystic carcinoma (2); allergic rhinitis (2); Erythema (2); Erythema nodosum (2); fetal growth restriction (2); focal glomerular sclerosis (2); gram-negative bacterial infections (2); Graves ophthalmopathy (2); idiopathic nephrotic syndrome (2); immune deficiency (2); in situ carcinoma (2); inflammatory myopathies (2); interstitial lung disease (2); Left ventricular diastolic dysfunction (2); Lewis lung carcinoma (2); meningococcal meningitis (2); non-Hodgkin lymphoma (2); non-melanoma skin carcinoma (2).
A further 145 diseases each share a sentence with MIF in 2 papers or fewer.